ZKSCAN5 (zinc finger with KRAB and SCAN domains 5)
Description:
May be involved in transcriptional regulation.
Synonyms: Zfp-95; ZFP95; ZNF914; ZSCAN37
Tractability: PROTAC: UniProt records ubiquitination sites on it; ubiquitination databases record sites on it.
Gene: Protein-coding gene on chromosome 7 (99,500,398 to 99,535,360, forward strand). Ensembl gene ENSG00000196652.
Subcellular location: Nucleus
Subcellular location (Human Protein Atlas): Intermediate filaments
Pathways (Reactome):
Gene expression (Transcription): Generic Transcription Pathway
Gene Ontology:
Molecular function: protein binding; DNA-binding transcription factor activity; DNA-binding transcription factor activity, RNA polymerase II-specific; RNA polymerase II cis-regulatory region sequence-specific DNA binding; zinc ion binding
Biological process: regulation of DNA-templated transcription; regulation of transcription by RNA polymerase II
Cellular component: nucleus
Genetic constraint (gnomAD): Loss-of-function variants: 31 observed, 70 expected, observed/expected ratio (o/e) 0.44, 90% interval 0.33 to 0.6. The upper end of that interval is the gene's LOEUF score, 0.6, which puts it in group 2 of 6, group 1 being the genes least tolerant of losing a copy. Missense variants: 881 observed, 1,090 expected, observed/expected ratio (o/e) 0.81, 90% interval 0.76 to 0.85. Synonymous variants: 361 observed, 392.77 expected, observed/expected ratio (o/e) 0.92, 90% interval 0.84 to 1.
Homologues: Orthologues: chimpanzee ZKSCAN5 (99% identical), macaque ZKSCAN5 (97% identical), dog ZKSCAN5 (88% identical), rabbit ZKSCAN5 (86% identical), guinea pig ZKSCAN5 (84% identical), pig ZKSCAN5 (84% identical), mouse Zkscan5 (79% identical), rat Zkscan5 (77% identical). Paralogues in human: ZNF250 (25% identical), ZNF16 (25% identical), ZNF189 (25% identical), ZNF227 (25% identical), ZNF33B (24% identical), ZNF606 (24% identical), ZNF229 (24% identical), ZNF658 (24% identical), ZNF41 (24% identical), ZNF595 (24% identical), ZNF708 (24% identical), ZNF7 (24% identical), and 164 more.
Diseases named in the same sentence as ZKSCAN5 in open-access papers:
ZKSCAN5 is named in the same sentence as 6 diseases in open-access papers, as found by Europe PMC text mining. Sharing a sentence is not in itself a finding about the gene and the disease. The quoted sentences say what the papers report.
breast carcinoma (3 papers, 2022 to 2025). "Clinically, the expression of ZKSCAN5 was frequently upregulated in patients with breast cancer and positively correlated with the expression of VEGFC and the number of lymphatic microvessels." (PMID 35600335, 2022). "To determine the phenotype of ZKSCAN5 in vivo, we examined the effect of ZKSCAN5 on breast cancer growth by injecting breast cancer cells containing this structure into the back of BALB/C nude mice." (PMID 35600335, 2022). "As a new clinical prognostic marker for breast cancer, ZKSCAN5 has a positive correlation with VEGFC expression." (PMID 35600335, 2022). "To further investigate the transcription mechanisms of ZKSCAN5 on regulating VEGFC expression in breast cancer cells, we confirmed the binding site of ZKSCAN5 on the VEGFC promoter." (PMID 35600335, 2022). "In conclusion, these findings imply the importance of ZKSCAN5 in lymphangiogenesis and the prognosis of breast cancer." (PMID 35600335, 2022). "Before this test, the specificity of the antibodies for ZKSCAN5 in IHC was determined by immunoblotting lysates from MDA-MB-231 and ZR75-1 breast cancer cells transfected with ZKSCAN5 siRNAs." (PMID 35600335, 2022). "We first performed immunohistochemistry (IHC) on 116 human breast cancer samples to demonstrate the clinical significance of ZKSCAN5." (PMID 35600335, 2022). "The conditioned medium of ZKSCAN5 knockdown breast cancer cells constrained tube formation, which could be rescued by ZKSCAN5 re-expression in the ZKSCAN5 knockdown cells." (PMID 35600335, 2022). "In addition, we found that ZKSCAN5 overexpression was positively correlated with a poor prognosis in patients with breast cancer." (PMID 35600335, 2022). "ZKSCAN5 was positively related to VEGFC expression in breast cancer tissues (p = 9.0 × 10−6)." (PMID 35600335, 2022). "ZKSCAN5 is a poor prognostic factor for patients with breast cancer." (PMID 35600335, 2022). "As expected, ZKSCAN5 knockdown significantly inhibited the growth of breast cancer tumours." (PMID 35600335, 2022). "In conclusion, ZKSCAN5 regulates breast cancer tumour growth and lung metastasis in vivo." (PMID 35600335, 2022). "Thus, targeting ZKSCAN5 will be an effective way to control lymphangiogenesis in breast cancer." (PMID 35600335, 2022). "The transcription factor zinc finger with KRAB and SCAN domains 5 (ZKSCAN5) activates VEGF-C expression by interacting with suppressor ensemble domain 7 (SETD7) to promote lymphangiogenesis, tumor growth, and metastasis of breast cancer." (PMID 41511312, 2025). "To the best of our knowledge, here, for the first time, we uncovered the function of ZKSCAN5 in modulating VEGFC expression, lymphangiogenesis, and breast cancer cell growth." (PMID 35600335, 2022). "Our results characterise the role of ZKSCAN5 in regulating VEGFC transcription and predict ZKSCAN5 as a breast cancer therapeutic target." (PMID 35600335, 2022). "Because ZKSCAN5 improved the secretion of VEGFC by breast cancer cells, the effects of the conditioned medium on HLEC proliferation and migration were investigated in ZKSCAN5 knockdown stable cell lines." (PMID 35600335, 2022). "ZKSCAN5 binds to the promoter section (−2,911 to −2,859 bp) of VEGFC in breast cancer cells." (PMID 35600335, 2022). "By regulating breast cancer-secreted VEGFC, ZKSCAN5 could induce the tube formation of lymph endothelial cells, which promotes tumour proliferation, migration, and metastasis." (PMID 35600335, 2022). "Furthermore, ZKSCAN5 is positively correlated with the expression of VEGFC and could be a valuable prognostic marker for poor survival of breast cancer." (PMID 35600335, 2022).
endometriosis (2 papers, 2022 to 2025). The growth of functional endometrial tissue in anatomic sites outside the uterine body. "We found that the locus of the ZKSCAN5 gene (rs34670419) in the composition of three multi-level (2,3,4 loci) most noteworthy intergenic interactions models is associated with endometriosis." (PMID 36430184, 2022). "The correlation of testosterone levels in patients with endometriosis with polymorphisms rs148982377 ZNF789 and rs34670419 ZKSCAN5 was shown." (PMID 41373783, 2025).
cholangiocarcinoma (1 paper, 2023). A carcinoma that arises from the intrahepatic biliary tree (intrahepatic cholangiocarcinoma) or from the junction, or adjacent to the junction, of the right and left hepatic ducts (hilar cholangiocarcinoma). "The rs187199523 locus has a binding site for the transcription factor ZKSCAN5 and is located on a related gene (RP11-563D10.1) intron, and RP11-563D10.1 is a long noncoding RNA (lncRNA), which might be associated with cholangiocarcinoma." (PMID 38003606, 2023).
cancer (2 papers, 2022 to 2024). A tumor composed of atypical neoplastic, often pleomorphic cells that invade other tissues. "Cancer cell-secreted VEGFC regulated by ZKSCAN5 controls HLEC proliferation, migration, and tube formation." (PMID 35600335, 2022). "Interestingly, ZKSCAN5 expression increased in cancer tissues compared to that in the adjacent paracancerous tissues (p = 2.33 × 10−6)." (PMID 35600335, 2022).
tumor (2 papers, 2022 to 2025). "ZKSCAN3, a transcription factor in the same family as ZKSCAN5, plays a role in many types of tumours." (PMID 35600335, 2022). "Tumours with high ZKSCAN5 expression had more lymph vessels compared with low ZKSCAN5 expression." (PMID 35600335, 2022). "In this study, we identified the role of the transcription factor zinc finger with KRAB and SCAN domains 5 (ZKSCAN5) in interacting with histone methyltransferase SETD7 and mediating VEGFC transcription and tumour lymphangiogenesis." (PMID 35600335, 2022). "In addition, ZKSCAN5 has been recognised as a novel critical regulator for the expression of VEGFC and contributes to tumour lymphangiogenesis." (PMID 35600335, 2022).
ZKSCAN5 also shares sentences with these, for which no sentence is quoted: angiosarcoma (1 paper).